RNU6-1333P (RNA, U6 small nuclear 1333, pseudogene)
Gene: Small nuclear RNA gene on chromosome 2 (238,028,971 to 238,029,063, reverse strand). Ensembl gene ENSG00000251971.
Homologues: Orthologues: chimpanzee U6 (99% identical), macaque U6 (90% identical), pig U6 (70% identical), mouse Gm24848 (68% identical), rat LOC120097657 (65% identical), dog U6 (62% identical). Paralogues in human: RNU6-1243P (76% identical), RNU6-727P (76% identical), RNU6-875P (76% identical), RNU6-1009P (75% identical), RNU6-24P (75% identical), RNU6-338P (75% identical), RNU6-537P (75% identical), RNU6-829P (75% identical), RNU6-879P (75% identical), RNU6-896P (75% identical), RNU6-1024P (74% identical), RNU6-1060P (74% identical), and 1285 more.